SOX2 (SRY-box transcription factor 2)
Diseases named in the same sentence as SOX2 in open-access papers (continued):
Sharing a sentence is not in itself a finding about the gene and the disease.
glioblastoma (continued). "A study reported the up-regulation of miR-145 using miRNA overexpressed vectors could improve the chemosensitivity of glioblastoma cells to demethoxycurcumin by targeting the SOX-2-Wnt/β-catenin axis." (PMID 37886001, 2023). "Also, TRIM24 promotes stemness and invasiveness of glioblastoma through direct activation of SOX2 expression and the induction of SOX2-targeted transcriptome." (PMID 36674511, 2023). "Due to the hypothesis that EGFRvIII is a marker of stem cells in glioblastomas or even in other cancers, EGFRvIII SOX-2 co-staining was conducted to address this question." (PMID 36292985, 2022). "Thus, IE1 protein promotes the presence of glioblastoma cancer stem cells through the induction of several stemness key markers, namely, SRY-Box Transcription Factor 2 (SOX2), Nanog, Nestin, and octamer-binding transcription factor 4 (OCT3/4)." (PMID 36366560, 2022). "Accumulated evidence indicates that several SOX members have been identified as tumor-specific antigens that can augment cytotoxic T lymphocytes (CTLs) response to kill cancer cells, including SOX2 (glioblastoma), SOX4 (lung cancer), SOX6 (glioblastoma), and SOX11 (glioblastoma)." (PMID 35267473, 2022). "Similarly, other studies have indicated that ER stress and UPR activation regulate glioblastoma stemness through SOX2 modulation." (PMID 35740372, 2022). "The potential of SOX2 re-expression to reverse the mesenchymal subtype into a more proneural subtype might open up strategies for novel glioblastoma treatments." (PMID 35701472, 2022). "The SOX2 in glioblastoma maintains stemness and oncogenic properties." (PMID 35538578, 2022). "Interestingly, ALKBH5 co-expressed with the typical stemness marker for glioblastoma, SOX2 and Nestin in tumor tissue." (PMID 35625706, 2022). "Thus, IE1 protein promotes the presence of glioblastoma cancer stem cells through its induction of SRY-Box Transcription Factor 2 (SOX2), Nanog, Nestin, and octamer-binding transcription factor 4 (OCT3/4), key markers of stemness." (PMID 35458542, 2022). "In further support of this positive relationship between TRIM26 and SOX2, in TCGA glioblastoma samples, we observed a significant correlation between TRIM26 and SOX2 mRNA expression levels, consistent with the ability of SOX2 to stimulate its own transcription." (PMID 34732716, 2021). "Thus, targeting these tumour-initiating and -propagating cells appears crucial to improve the survival rates of glioblastoma patients and requires detailed understanding of key glioblastoma stemness regulators, such as SOX2." (PMID 33924599, 2021). "Importantly, SRR2-deleted glioblastoma cells presented reduced SOX2 expression and decreased proliferative activity and self-renewal capacity in vitro." (PMID 33805518, 2021). "SOX2 is required for the maintenance of glioblastoma stem cells (GSCs)." (PMID 34732716, 2021). "In this study SOX2 was initially identified as an inducer of glioblastoma subtype transition in an experimental overexpression-screen, and subsequently SOX2 was found through a CMap analysis to be at the apex of gene expression determination in glioblastoma cultures." (PMID 34021259, 2021). "In order to delineate how DYRK1A downregulates SOX2 expression, we analysed our proteomic and phosphoproteomic data obtained from U251 glioblastoma cells infected with doxycycline (DOX)-inducible DYRK1A shRNA (sh-DYRK1A U251) or treated with DYRK1A inhibitor ALGERNON." (PMID 33924599, 2021). "SOX2, which is a transcription factor necessary for the maintenance of glioblastoma stem cell tumorigenic activity, is commonly used to detect the stem cell population in glioblastoma." (PMID 34298643, 2021).
glioblastoma (continued). "Alone or in cooperation with Sox2, Nanog and other members, Oct4 activates both protein-coding genes and noncoding RNAs necessary for pluripotency and self-renewal of glial stem cells reprogramming glioblastoma and other cancers." (PMID 34613998, 2021). "In summary, HIF1α and HIF2α regulate glioblastoma malignant progression through the EGFR–PI3K/AKT pathway via a positive feedback mechanism under the effects of Sox2 and Klf4, which provides a new tumour development model and strategy for glioblastoma treatment." (PMID 33762574, 2021). "High expression of SOX2 has been found in glioblastoma, breast, and cervical CSC populations." (PMID 34123800, 2021). "Moreover, its expression is a recognized marker of the proneural subtype of glioblastomas and, even more importantly, in cooperation with Sox2, Pou3f2 and Sall2, Olig2 is a key master transcription factor of glioblastoma-initiating cells." (PMID 32316617, 2020). "Sox2 regulates proliferation, migration, invasion, and colony formation of glioblastoma cells." (PMID 32682409, 2020). "The interaction between NEAT1, miR-132, and SOX2 has an important role in glioblastoma." (PMID 32283739, 2020). "The NEAT1/miR-132/SOX2 axis regulates glioblastoma cells invasiveness, and, therefore, could be explored for treatment of this tumor type." (PMID 32283739, 2020). "Similarly, knockdown of Sox2 was found to efficiently inhibit in vitro sphere formation and reduced tumor formation in glioblastoma and gastric cancer, respectively." (PMID 29401647, 2018). "Additionally, SOX2 knockout in glioblastoma stem cells isolated from human glioma tumor inhibits cell proliferation and tumorigenicity in immunodeficient mice." (PMID 29849920, 2018). "High expression of SOX2 has been correlated with tumor progression of oral squamous cell carcinoma, hepatocellular carcinoma, colorectal cancer, glioblastoma and others." (PMID 30186173, 2018). "Moreover, it has also been reported that the Chip-seq on a Sox2 immuno-precipitate shows a highly efficient binding of Sox2 to the IL6 promoter in glioblastoma or ES cells." (PMID 29337886, 2018). "The inhibition of switch genes highly correlates with the activation of genes related to neural development and differentiation, such as the 4-core OLIG2, POU3F2, SALL2, SOX2, whose induction has been shown to be sufficient to reprogram differentiated glioblastoma into stem-like cells." (PMID 30497369, 2018). "Our results also showed that metformin significantly suppressed self-renewal capacity of glioblastoma stem cells (GSCs), and expression of stem cell markers Bmi1, Sox2 and Musashi1, indicating that metformin can inhibit cancer stem-like properties of GBM cells." (PMID 29467947, 2018). "In addition, BP decreases the expression of SOX2 by reducing its metastasis and invasiveness in glioblastoma multiform (GBM) cell." (PMID 30287739, 2018). "ZEB1 is a target of SOX2 and has been shown to be co-expressed with SOX2 in glioblastoma." (PMID 29152086, 2017). "Interestingly, hypomethylation of the SOX2 promoter was detected in over 250 glioblastoma specimens compared to normal patient controls." (PMID 28388544, 2017). "Interestingly, when cells were grown in 2D, the expression levels of OCT4, BMI1, SOX2 for melanoma cells and of SOX2 for glioblastoma were modulated by BCL-XL overexpression." (PMID 29238043, 2017). "Indeed, we identified that there is an inverse correlation between MKP1 and SOX9 and SOX2 expression in glioblastoma samples." (PMID 29284798, 2017). "Conversely, treatment of GSCs with iloprost resulted in a significant increase in expression of the GSC marker Sox2, and an associated decrease in expression of the differentiation markers, GFAP and β-tubulin, in multiple GSCs and the U87 glioblastoma cell line." (PMID 29137258, 2017).
glioblastoma (continued). "More than that, accumulating studies suggest that SOX2 acts as an oncogene in some cancers, such as skin squamous-cell carcinoma, lung squamous-cell carcinoma, ovarian carcinoma, osteosarcomas and glioblastoma." (PMID 29296232, 2017). "Going forward, it will be interesting to determine whether RMST and MEG3 are commonly expressed in SOX2-positive tumors, including glioblastoma and medulloblastoma." (PMID 28388544, 2017). "Melatonin also decreased SOX2 expression in glioblastoma CSCs6." (PMID 29213108, 2017). "Similarly, studies of glioblastoma, esophageal, breast, and prostate cancers have reported that SOX2 levels increase with increasing tumor grade, and for prostate cancer the percentage of SOX2-positive cells correlates with Gleason score." (PMID 28388544, 2017). "Several studies have started to characterize downstream targets of SOX2 in glioblastoma." (PMID 27822457, 2016). "Additionally, SOX2 genetic amplification and promoter DNA hypomethylation has been identified in a set of GBM patients, further expanding the mechanism responsible for SOX2 upregulation in glioblastoma samples and GSCs." (PMID 27822457, 2016). "Mer receptor expression is maintained in primary glioblastoma-derived tumor spheres and correlated with the expression of Nestin and Sox2 in a glioblastoma spheroid culture model, suggesting that Mer is crucial for the maintaining an undifferentiated state of cells." (PMID 27028863, 2016). "Altogether both works provide clues regarding SOX2 functions in glioblastoma." (PMID 27669421, 2016). "Furthermore, in GBM glioblastoma cells, CA promoted apoptosis by inducing cell cycle arrest and degradation of cyclin B1, RB, SOx2 and GFAP, molecules involved in cell survival and maturation processes." (PMID 27869665, 2016). "In addition, a recent study demonstrated that OPN silencing suppressed transcriptions of key stemness transcription factors SOX2, Oct3/4, and Nanog in vitro and glioblastoma stem-like cell character and tumorigenicity in vivo." (PMID 26106421, 2015). "Moreover, several studies have shown over-expression of SOX2 in various cancers including glioblastoma, non-small cell lung cancer, prostate cancer and hepatocellular carcinomas supporting SOX2 as a relevant oncogene in these malignancies." (PMID 24404135, 2014). "The effects of elevating SOX2 in glioblastoma led us to examine whether elevating SOX2 also influences the growth of medulloblastoma tumor cells." (PMID 22937156, 2012). "U87 glioblastoma cells were engineered to enable the inducible expression of SOX2 controlled by a tet-responsive element, which could be activated by adding doxycycline (Dox) to the medium." (PMID 22937156, 2012). "Thus, both medulloblastoma and glioblastoma cells cannot readily overcome the effects of elevated SOX2 levels, even after 4 weeks in culture." (PMID 22937156, 2012). "Sox2 expression was regulated by PLK1 in glioblastoma multiform cells and PLK1 inhibition could delay tumor progression in mice." (PMID 23554769, 2012). "Increased expression of the transcription factor SOX2 has been reported in a growing list of tumors, including breast, prostate, lung and in a number of highly aggressive central nervous system neoplasms, including both glioblastoma and medulloblastoma." (PMID 22937156, 2012). "Additionally, it has recently been reported that the SOX2 gene is amplified in nearly 10% of glioblastomas and overexpressed in over 85% of these tumors." (PMID 22937156, 2012). "To determine whether the dramatic phenotypic changes observed in U87 cells upon ectopic SOX2 expression could be extended to other glioblastoma lines, we performed similar analyses in U118 glioblastoma cells." (PMID 22937156, 2012). "Moreover, the knockdown of SOX2 has been shown to decrease the proliferation and tumorigenicity of glioblastomas." (PMID 22937156, 2012). "Recently, we reported expression of the stem cell marker SOX2 in glioblastoma specimens." (PMID 22070920, 2011).
glioblastoma (continued). "Moreover, our analyses revealed a downregulation of HEF1/NEDD9 and of metallo-matrixproteases pro-MMP1 and pro-MMP2 in SOX2-depleted U343-MG and U373-MG glioblastoma cells." (PMID 22070920, 2011). "All glioblastoma cells with multilineage phenotype were also SOX-2 positive." (PMID 19216795, 2009). "Clinical samples further confirmed the co-upregulation of NIBAN2, FLII, and RREB1 in GBM (Glioblastoma) tissues, which correlates with SOX2 and Ki-67 expression and poor prognosis." (PMID 41736673, 2026). "Furthermore, it was confirmed that the cytotoxicity of polydatin was associated with the inhibition of the EGFR-Akt/ERK1/2/STAT3-sex-determining region Y-box 2 (SOX2)/Snail signaling pathway, of which several components were essential therapeutic targets for glioblastoma." (PMID 39690423, 2024). "Hence, interfering with SOX2 nuclear translocation by small molecules able to antagonize SOX2-importin interaction may provide an additional therapy perspective for glioblastoma, and possibly other SOX2-dependent tumors." (PMID 35626641, 2022). "Also, SOX2 mediates transcription of ABCC3 in glioblastoma cells." (PMID 36585418, 2022). "A growing body of evidence supports the presence of a population of cells in glioblastoma (GBM) with a stem cell-like phenotype which shares certain biological markers with adult neural stem cells, including expression of SOX2, CD133 (PROM1), and NES (nestin)." (PMID 36333778, 2022). "Its effect on a subpopulation of GBM cells exhibiting glioblastoma stem cell (GSCs)-like characteristics revealed a reduced expression of Oct4, Sox2, CD133, CD44, and a decrease in ALDH+, Nestin+ and CD44+ cells." (PMID 36231019, 2022). "VX-984 inhibition of DNA-PK in patient-derived xenographs model sensitizes glioblastoma multiforme (GBM) to doxorubicin, and radiation treatments induced differentiation of GB stem cells by altering the stability of Sox2 leading to growth arrest." (PMID 36011043, 2022). "Further, our observations in glioblastoma provide the rationale for future studies to elucidate additional regulators of SOX2 protein stability in GSCs and suggest that SOX2-specific UPS-based strategies might represent a potentially viable avenue to therapeutically target GSCs." (PMID 34732716, 2021). "However, in glioblastoma KLF4 expression appears negatively correlated with SOX2 expression." (PMID 34021259, 2021). "Several studies describe how SOX2 expression is elevated in a large proportion of cancers, including brain tumors such as glioblastoma (GBM)." (PMID 33805518, 2021). "The reduction of SOX2 expression we found following SB747651A exposure could be linked to the decreased fraction of treated tumor cells with spheroid formation abilities, since SOX2 is a crucial stemness and self-renewal protein in glioblastomas." (PMID 33727611, 2021). "GSI RO4929097, in combination with radiation and TMZ, decreases the expression of CD133, SOX2, and nestin (inducing neural and astrocytic differentiation), has an anti-proliferative effect (reducing 3D spheroid growth), and increases the survival of the orthotopic Glioblastoma mouse model." (PMID 30832246, 2019). "Sex determining region Y-box protein 2 (SOX2), a transcription factor involves in pluripotency induction and maintenance of cell stemness, has been proved to be aberrantly expressed in various solid tumors including breast cancer, lung cancer, prostate cancer, glioblastomas and melanomas." (PMID 30053878, 2018). "Thus, it will be interesting to determine whether TUNA is expressed in glioblastoma and medulloblastoma and other SOX2-positive tumors, where it may also contribute to SOX2 expression." (PMID 28388544, 2017). "Finally, we examined the protein levels of the stem cell markers sox2 and nestin in the primary glioblastoma cell line T269 after DHA treatment to assess whether DHA can induce differentiation." (PMID 27447560, 2016). "Therefore, SOX2 and its downstream effectors would be targets for glioblastoma therapy." (PMID 23998913, 2013).
glioblastoma (continued). "To determine whether exogenous SOX2 expression could impair the long-term growth of other brain tumors types, we stably engineered U87 glioblastoma cells for Dox-inducible expression of SOX2 (i-SOX2-U87) using the same lentiviral vectors used to engineer i-SOX2-DAOY cells." (PMID 22937156, 2012). "We undertook this study to understand how the transcription factor Sox2 contributes to the malignant phenotype of glioblastoma multiforme (GBM), the most aggressive primary brain tumor." (PMID 22069467, 2011). "SOX2 appears to re-activate in several human cancers including glioblastoma multiforme (GBM), however, the detailed response program of SOX2 in GBM has not yet been defined." (PMID 21211035, 2011). "In our previous study we detected the stem cell marker and transcription factor SOX2 in glioblastoma tissue and glioblastoma cell lines and hypothesized that it might represent an ideal target for an experimental RNAi approach for treatment of malignant gliomas." (PMID 22070920, 2011). "The association of transcription factors, Sox2 (responsible for stemness) and Twist1 (responsible for EMT) thus provides a platform to correlate the stem cell pathway with EMT pathway, which can be further studied to address potential targets for glioblastoma cure." (PMID 22184289, 2011). "In glioblastoma specifically, lncRNAs promote GSC maintenance and confer chemoresistance via several different mechanisms, including the modulation of SOX2, a master regulator of stemness." (PMID 39323013, 2025). "The reprogramming of differentiated glioblastoma cells into CSCs was only possible when four essential transcription factors‐POU3F2, SOX2, SALL2 and OLIG2 were re‐expressed." (PMID 40665579, 2025). "Transcription factors like ASCL1, HES1, OLIG2, SOX2, and NOTCH-ligands (DLL1/3) play crucial roles in GBM plasticity by maintaining a pool of quiescent glioblastoma stem cells (GSCs)." (PMID 40358199, 2025). "For example, in glioblastoma, under hypoxic conditions, hypoxia‐inducible factor‐1α (HIF‐1α) can stabilise the protein level of SOX2 by inhibiting its ubiquitination and degradation process, thereby maintaining the self‐renewal ability of CSCs." (PMID 40665579, 2025). "SOX2 overlapping transcript (SOX2OT) is highly expressed in embryonic stem cells and upregulated in various cancer types, including glioblastoma." (PMID 39015773, 2024). "As a result of 2 mg/mL OLE application in glioblastoma CSCs, a decrease in OCT4 and SOX2 gene expressions, which are the target of miR-137, has been reported." (PMID 38722566, 2024). "ITGB8 has also been found to enrich glioblastoma stem cells (GSCs), with co-expression of ITGB8 and the stemness marker SOX2 observed in ITGB8 (+) glioblastoma cells." (PMID 39239559, 2024). "In neurosphere assays of human glioblastoma cell lines, silencing METTL3 reduces the expression of glioblastoma reprogramming factors POU3F2, SOX2, SALL2, and OLIG2, and inhibits glioblastoma cell proliferation." (PMID 39473440, 2024). "VP has also been shown to suppress expression of YAP/TAZ transcriptional targets (SOX2, C-MYC, and EGFR) in human patient-derived glioblastoma stem cells and confer significant survival benefit in the Drosophila GBM model." (PMID 36983079, 2023). "In glioblastoma, H3K9me2 modification of CD133 and Sox2 is important in regulating CSC self-renewal." (PMID 37853437, 2023). "In glioblastoma stem cells (GSCs), for example, the expression levels of key stemness-related TFs (POU3F2, SOX2, SALL2, and OLIG2) are significantly higher than those in more differentiated tumor cells." (PMID 37370081, 2023). "According to a glioblastoma (GBM) study, DNA-PK stabilizes SOX2 by phosphorylating it, which promotes treatment resistance by malignantly progressing glioma stem-like cells (GSCs) in a stem cell state." (PMID 37322433, 2023). "Increased PROM1, SOX2, Fibronectin, and RPSA transcripts level were also observed in clinical grade IV glioblastoma tissues compared to normal tissue." (PMID 36497426, 2022).